TNF (tumor necrosis factor)
Diseases named in the same sentence as TNF in open-access papers (continued):
Sharing a sentence is not in itself a finding about the gene and the disease.
tumor (continued). "Through bioinformatics analysis of the sequencing results, they found that TNF‐α+ Tregs can be recruited into tumour tissues and affect patient survival." (PMID 40665579, 2025). "This was further confirmed by elevated IFNγ+ and TNFα+ cytotoxic CD8+ T cells within the Cyp11a1cKO tumour milieu." (PMID 40287432, 2025). "At high quantities, TNF-α promotes death in tumor cells and attracts immune cells to the tumor site, enhancing local immune responses." (PMID 40309351, 2025). "M1-macrophages phagocytic tumor cells or secrete cytokines such as NO, ROS, IL-12 and TNF-α to enhance anti-tumor immune response." (PMID 41333839, 2025). "Various cytokines, such as IL‐1, IL‐6, and TNF‐α, as well as adipokines such as leptin and adiponectin, significantly impact tumor cell proliferation and invasion." (PMID 39652453, 2025). "M1‐polarized macrophages are known to secrete high levels of IL‐1β and TNF‐α, which exert antiproliferative effects and can effectively kill tumor cells." (PMID 41306557, 2025). "To investigate the mechanism by which the essential oil contributed to tumor growth inhibition, we first measured the circulating levels of IL-12, TNF-α, and IFN-γ in sera." (PMID 40429884, 2025). "On the other hand, TNF-α can facilitate tumor growth by promoting the survival and proliferation of neoplastic cells through the nuclear factor-κB signaling pathway." (PMID 40227584, 2025). "Upon activation by ω-3 LCPUFAs, PPARγ directly affects the NF-κB pathway and downregulates the level of pro-inflammatory factors such as MCP-1, IL-6, and TNF-α, so as to suppress neoplasia development." (PMID 39834867, 2025). "M1 macrophages, activated by signals like IFN-γ and LPS, produce pro-inflammatory cytokines (e.g., TNF-α and IL-12) and reactive species that help eliminate tumor cells." (PMID 40563651, 2025). "IFN-γ and TNF-α are also the key effector cytokines in anti-tumor immunity; one mechanism is ascribed to their role in triggering cell death." (PMID 40564173, 2025). "The TNF/IL-17 signaling pathway plays a crucial role in the inflammatory tumor microenvironment, promoting tumor progression and resistance to apoptosis." (PMID 40141200, 2025). "Arginine-based pseudo-proteins also stimulate the production of nitric oxide (NO), resulting in cell cycle arrest, tumor cell cytostasis, or apoptosis and further sensitizing cancer cells to TNF-α-induced cytotoxicity." (PMID 40648713, 2025). "BGN is predominantly expressed by CAFs in the tumor microenvironment and interacts with Toll-like receptors (TLR2 and TLR4), which associate with TGFβ/Snail and TNFα/NF-κB signaling pathways to regulate EMT." (PMID 40977686, 2025). "Our findings were supported by Shishodia and Aggarwal, who found that diosgenin effectively prevented the activation of NF-κB induced by TNF-α and inhibited the formation of osteoclasts in tumor cells." (PMID 40283888, 2025). "This transition is marked by increased expression of pro-inflammatory cytokines (e.g., TNF-α, IL-12) and enhanced ROS-mediated cytotoxicity, leading to tumor cell apoptosis and delayed tumor progression in murine models." (PMID 40387965, 2025). "In the cancer cohort, TNF-α significantly correlated with several tumor markers—particularly CA19-9 and CA72-4—underscoring TNF-α’s role in tumor-related processes." (PMID 40299527, 2025). "In HCC, neutrophils contribute to tumor progression through IL-6 and TNF-α-mediated inflammation, promoting angiogenesis and immune suppression via mechanisms involving arginase-1 and ROS." (PMID 40387965, 2025). "COX-2 expression correlated with tumor size (p = 0.01), whereas high TNF-α expression was noted in moderately/poorly differentiated OSCC." (PMID 41259576, 2025). "Tumor cells induce inflammation by activating white blood cells and releasing inflammatory cytokines (e.g., TNF-α, IL-1β, IL-6, IL-21, and TGF-β), which are critical at the tumor site." (PMID 41153842, 2025).
tumor (continued). "Proinflammatory cytokines, such as tumor necrosis factor-alpha (TNF-α), interleukin-1 beta (IL-1β), and interleukin-6 (IL-6), play a crucial role in shaping a proinflammatory tumor microenvironment." (PMID 40002704, 2025). "TIC10 is a small molecule imipridone that can upregulate endogenous tumor necrosis factor (TNF)‐related apoptosis‐inducing ligand (TRAIL) levels within tumor cells." (PMID 40673385, 2025). "Reflecting its dual function, despite its pro-tumor role, TNF also has apoptotic effects on tumor cells." (PMID 41376630, 2025). "Beyond antibody secretion, these plasma cells also produce a spectrum of cytokines such as tumor TNF, IL-2, IL-6, and IFN-γ." (PMID 41285707, 2025). "Neutrophils are innate immune cells in TME, which present two phenotypes: the (i) N1 (anti-tumor phenotype) that produces reactive oxygen species (ROS), tumor necrosis factor-α(TNF-α), and intercellular adhesion molecule 1 (ICAM-1)." (PMID 41369383, 2025). "Studies have shown that tumor necrosis factor (TNF)-α and lymphotoxins, mainly produced by activated lymphocytes and NK cells, are essential for the formation of tumor-associated HEVs in mouse models." (PMID 40107247, 2025). "Curcumin inhibits tumor growth by reducing the levels of pro-inflammatory cytokines (e.g., TNF-α, IL-8, IL-6, and IL-1), also down-regulating the protein expressions of these cytokines." (PMID 40490812, 2025). "Functional enrichment analysis indicates that ECI2 is inversely associated with several tumor proliferation signaling pathways, including PI3K/AKT, Wnt, and TNF signaling pathways." (PMID 40432805, 2025). "The term “TNF” refers to a cytokine that was first identified as a tumor necrosis-inducing molecule in 1975 and possesses the ability to kill or inhibit tumor cells." (PMID 40136649, 2025). "Cytokines such as interferon-γ and TNF-α, secreted by lymphocytes, suppress tumor cell proliferation and invasion while also inducing apoptosis." (PMID 40004836, 2025). "Cytokines such as TGF-β, IL-6, IL-10, and TNF-α play critical roles in tumor progression and metastasis." (PMID 40443678, 2025). "By contrast, M1 macrophages, though less well classified and capable of subtype interconversion, dominate early tumor stages, releasing TNF-α, CXCL9, CXCL10, iNOS, and ROS to induce inflammation and eliminate tumor cells." (PMID 40948759, 2025). "In patients, however, TANs have been reported to be recruited by chronically produced TNF-α in an IL-17-dependent manner as well as being involved in tumor promotion." (PMID 40369674, 2025). "For example, CD11b+ myeloid cells enhance the anti-tumor activity of B cells by producing high levels of TNF-α, which promotes B cell activation and proliferation." (PMID 41285707, 2025). "The robust TNF-α–CA19-9 correlation observed in our study reinforces the concept that TNF-α rises in tandem with tumor bulk and metastatic potential." (PMID 40299527, 2025). "Concurrently, pro-inflammatory cytokines, including IFN-γ, TNF-α, and IL-2, are secreted, enhancing the anti-tumor response and facilitating the recruitment of additional immune cells into the tumor microenvironment." (PMID 40805178, 2025). "Like NK cells, macrophages produce pro-inflammatory cytokines like interleukin 6 (IL-6) and tumor necrosis factor-alpha (TNF-α), as well as reactive oxygen/nitrogen species, which are crucial for both innate host defense and tumor cell death." (PMID 40234973, 2025). "Tumor necrosis factor α (TNFα) is a prominent tumor-promoting cytokine that facilitates carcinogenesis across several cancer types." (PMID 40869207, 2025). "Innate immune cells, such as mature dendritic cells and M1-tumor-associated macrophages (TAM), produce cytokines (IFN-α, IL-12, IL-18, or TNF-α) and chemokines (CXCL9, CXCL10, or CCL21) that suppress tumor angiogenesis." (PMID 41373757, 2025).
tumor (continued). "The engineered probiotic E. coli Nissle 1917 strain has been reported to enhance the antitumor ability and efficacy of immunotherapies by increasing the concentration of L-arginine in TME and the number of tumor-infiltrating T cells that produce TNF." (PMID 40568973, 2025). "In our experiments, the interaction of anti‐ROR1 CAR T‐cells with ROR1‐expressing tumor cells in the IAC model was associated with the release of proinflammatory cytokines, including TNF, IL‐6, and IFN‐γ." (PMID 40249196, 2025). "M1 macrophages, activated by signals such as IFN-γ and LPS, play a tumor-suppressive role by producing pro-inflammatory cytokines like IL-12 and TNF-α, promoting effector T cell responses, inducing tumor cell apoptosis, and inhibiting angiogenesis." (PMID 40764998, 2025). "Histamine, tumor necrosis factor α (TNF-α), interleukin (IL)-10, pro-angiogenetic factors, and proteases favor tumor progression and metastasis, whereas tryptase and IL-5 appear to exert anti-neoplastic effects." (PMID 39940696, 2025). "CD8+ T cells can release Perforin and granzyme, and also secrete tumor killing factors like TNF-α and IFN-γ, which specifically recognize and kill cancer cells, and can activate other immune cells." (PMID 41179305, 2025). "We observed IKE treatment markedly upregulated TNF-α level and downregulated Arg-1 level in WT and Lnk-/- tumor MDSCs." (PMID 40796725, 2025). "Intracellular flow cytometry analysis of the effector cytokines IFNγ and TNF, which have direct anti-tumor properties, showed a significant increase in IFNγ and TNF expression by NK cells upon treatment with 8H8_SDIE." (PMID 40821788, 2025). "This combined effect in the tumor microenvironment can contribute to immune cell dysfunction and help tumor cells evade the immune system.Conversely, in specific situations, IL-6 and TNF-α can show opposing effects." (PMID 40242775, 2025). "Following antigen activation, CD8+ T cells unleash a plethora of effector molecules, including cytokines (e.g., IFN-γ and TNFα) and cytotoxic agents inducing cell death (e.g., granzymes and FasL), which are integral to the process of tumor rejection." (PMID 40397730, 2025). "In the MC38 tumor model, the TIL landscape changes in response to checkpoint blockade, as a switch from an NKT-driven TNFα response to a T-cell-driven IFN-γ response has occurred in the tumor microenvironment." (PMID 39941003, 2025). "Studies have shown that exercise can slow tumor metastasis by reducing the levels of proinflammatory factors, such as IL-6 and TNF-α." (PMID 40370453, 2025). "Long-term lack of sleep is also associated with increased inflammation, higher rates of cancer, and accelerated tumor progression due to elevated levels of proinflammatory cytokines such as Interleukins 1 and 6 (IL-1, IL-6) and Tumor Necrosis Factor (TNF)." (PMID 40700251, 2025). "M1 macrophages are activated by inflammatory stimuli, producing cytokines such as TNF-α and IL-12, which enhance immune responses and inhibit tumor growth." (PMID 40242222, 2025). "TNF-α is recognized for its cytotoxic properties and plays a key role in the anti-tumor activity of macrophages." (PMID 41017127, 2025). "Previous investigations revealed that emodin can diminish TNF-α–mediated PD-L1 stabilization or enhance the tumor-killing effects of CD8+ T cells in patients with breast cancer." (PMID 40804393, 2025). "CD4+ T cells secrete cytokines such as IFN-γ and TNF, which directly limit tumor growth and modulating the immunogenicity and vascularization of the tumor microenvironment (TME)." (PMID 40458394, 2025). "In this study, we elucidate the changes in the tumor microenvironment during bone invasion and identify the critical role of newly defined TNF-α + TAMs in promoting bone invasion of PitNETs." (PMID 39865310, 2025). "Polymorphisms in genes encoding cytokines (IL6, TNF, and IL10) and HLA molecules influence the liver’s immunological tolerance and tumor surveillance capacity." (PMID 40869967, 2025).
tumor (continued). "Conversely, prolonged low-level TNF-α expression can accelerate inflammation-induced tumor development." (PMID 40309351, 2025). "GM-CSF contributes to an immunosuppressive GBM TME, and TNF-α and IL-1 promote tumor invasion, tumor cell migration, and angiogenesis." (PMID 40563634, 2025). "Administration of EpCAM-CAR-T cells in CRC xenograft inhibited tumor growth and increased cytotoxic cytokines tumor necrosis factor-α (TNF-α) and IFN-γ." (PMID 40647402, 2025). "In vitro studies have further demonstrated that activation of the TNF-α axis induces invasive behavior in BC cells, while TNF-α more broadly promotes tumor progression by enhancing cellular migration within the TME." (PMID 41153842, 2025). "They secrete anti-tumor cytokines (IFN-γ and TNF-α), and cytotoxic molecules such as perforin and granzyme-B, effectively killing HLA-null tumor cell lines like K562 cells." (PMID 40110110, 2025). "Tumor-Nekrose-Faktor(TNF)- und Januskinase(JAK)-Inhibitoren sind breit wirksam, auch bei extraintestinalen Krankheitsmanifestationen." (PMID 39747696, 2025). "Their functional maturation is promoted by cytokines such as IL4, IL6, IL13, and TNF, while mobilization into the tumor niche is orchestrated by chemoattractants including IL8, CCL2, and CXCL12." (PMID 41155172, 2025). "Programmed cell death processes in tumor cells are also triggered in response to other inflammatory cytokines such as TNF, IL-1β, MCP-1 (monocyte chemotactic protein 1), and others." (PMID 40821768, 2025). "GO and KEGG pathway analyses identified signaling networks critical for tumor immune surveillance and evasion, with the TNF signaling pathway exhibiting a prominent role." (PMID 41155558, 2025). "NK cells as an important component of the anti-tumor immune response, exert anti-tumor immune functions through the secretion of cytokines such as IFNγ and TNFα." (PMID 40356913, 2025). "The concept of anti-TNF therapy (using agents like infliximab or etanercept) has shown promise in other malignancies and inflammatory conditions by reducing tumor-promoting inflammation." (PMID 40299527, 2025). "N2 neutrophils secrete pro-inflammatory cytokines, such as IL-1β and TNF-α, which can exacerbate the inflammatory milieu and create conditions that favor tumor cell survival and dissemination." (PMID 40486595, 2025). "Correlation analyses and multivariate regression were performed to assess the relationship of TNF-α with tumor markers, inflammatory indices, and disease stage." (PMID 40299527, 2025). "Again, PP2A-deficient CD8+ T cells exhibited reduced tumor infiltration and fewer cells expressed IFN-γ, TNF-α, and GZMB." (PMID 39759159, 2025). "Anti-MUC1-CAR4 T cells achieve anticancer effects on MUC1-expressing CCA cells by increasing the production of anti-tumor cytokines (TNF-α and IFN-γ), pro-apoptotic proteins (granzyme B), and by inducing lysis of CCA cells." (PMID 40070825, 2025). "Engaged CD8 T cells release a barrage of cytokines during their attack on target tumor cells, including interferon-gamma (IFNg), tumor necrosis factor (TNF), and TNF-related apoptosis-inducing ligand (TRAIL)." (PMID 41315176, 2025). "Through genetic engineering, researchers have developed various L19-based immunocytokines to deliver cytokines such as IL-2, TNF, and IL-12 and studied their biodistribution in tumor-bearing mice after systemic administration." (PMID 40557148, 2025). "A key mechanism involves the chronic inflammatory tumor microenvironment, where malignant B cells and stromal components release cytokines (e.g., IL-6, TNF-α), chemokines, ROS, and growth factors." (PMID 41516229, 2025).
tumor (continued). "Tumor microenvironmental factors such as IL-1β, IL-6, TNF-α, and IFN-γ, promote IMCs accumulation, inhibit their differentiation, and activate their immunosuppressive functions, at which point they are referred to as MDSCs." (PMID 40822347, 2025). "The increase in forward scatter median following Pam3CSK4 stimulation suggests heightened neutrophil activity, leading to the secretion of cytokines and chemokines like TNF, IL-6, and IL-8, which promote tumor cell proliferation, invasion, and metastasis." (PMID 39960903, 2025). "When the CNS is exposed to infection, injury, or tumor stimuli, it rapidly initiates defense mechanisms by releasing cytokines (e.g., IL-1β, TNF-α) and chemokines (e.g., CXCL10, CCL2)." (PMID 40092993, 2025). "It has an immunomodulation potential, since it aims to reprogram the TME through cytokines such as TNF and IFNα, enabling a more effective anti-tumor response." (PMID 41208963, 2025). "Differential expression analysis revealed that CASP4, CHMP4B, ELANE, IL-1A, and TNF were significantly upregulated in tumor samples (p < 0.05)." (PMID 40538398, 2025). "In early-stage or MSI-H CRC, they can exert anti-tumoral effects via secretion of ROS and TNF-α, directly damaging tumor cells." (PMID 41244711, 2025). "Synergistically, these perturbations activate NF-κB/STAT3 signaling, generating a pro-inflammatory cytokine milieu (IL-6, TNF-α, IL-1β) that promotes tumor progression through autocrine-paracrine cascades." (PMID 40919140, 2025). "Pathway analyses indicated a difference in immune/inflammatory related signatures between the two primary tumours, such as an enrichment of DEGs in the NF-kappa B signalling and TNF signalling pathways." (PMID 40438247, 2025). "Bioinformatics analysis has shown that several proteins interacting with MES are strongly associated with tumor progression, including PAK1, TNF, SRC, and CDC25A." (PMID 40699726, 2025). "In BC, the genes STAT3, CTNNB1, and MYC were upregulated, while TNF was downregulated in tumor tissues." (PMID 41186627, 2025). "To investigate this, we conducted affinity purification of the TNFR1 complex in both sensitized and resistant tumor cells upon short-term stimulation of biotin-labeled TNF and analyzed the samples by LC-MS." (PMID 41315176, 2025). "For example, IL-1 and TNF encourage the adhesion of tumour cells to endothelial cells in a dose and time-dependent manner." (PMID 41440367, 2025). "Specifically, these glucans stimulate monocytes and macrophages to release pro-inflammatory cytokines such as IL-6, IL-1β, and TNF-α, thereby enhancing immune responses and inhibiting tumor growth, even with a relatively loose helical configuration." (PMID 40035898, 2025). "M1 macrophages orchestrate anti-tumor immunity by secreting pro-inflammatory cytokines, including TNF-α and IL-12." (PMID 41285707, 2025). "Tumor-infiltrating lymphocytes secrete a variety of cytokines, such as IFN-γ and TNF-α, which not only inhibit tumor growth but also promote tumor cell apoptosis." (PMID 40777110, 2025). "TAMs generally exhibit two polarization states: M1 (classically activated, tumoricidal) enhance antitumor immunity by secreting TNF‐α, IL‐1β, and IL‐6, and producing nitric oxide and ROS, directly killing tumor cells and inhibiting tumor growth." (PMID 40900811, 2025). "Consistent with this, TNF‐α‐stimulated NT tumour cells displayed a significant enhancement in adhesion to HUVEC." (PMID 40488391, 2025). "Initially, TNF was identified owing to its tumor-fighting properties; however, it is now recognized as a critical mediator in inflammation." (PMID 40564167, 2025). "Hemocyte-derived Eiger (Egr)/Tumor necrosis factor α (TNFα) thereupon induces JNK-dependent tumor cell death." (PMID 40143968, 2025). "Neutrophils produce pro-inflammatory cytokines, such as IL-1β and TNF-α, which can enhance tumor cell proliferation and survival." (PMID 41180630, 2025).